CRP (C-reactive protein)
Diseases named in the same sentence as CRP in open-access papers (continued):
Sharing a sentence is not in itself a finding about the gene and the disease.
pneumonia (continued). "For instance, patients with CRP levels <20 mg/L should not have been prescribed antibiotics unless they were <5 years old and met World Health Organization criteria for pneumonia, according to the algorithm." (PMID 37490743, 2023). "CRP ≥15.8 mg/dL is an ideal promising predictor of pneumonia in AECOPD, and its plasma level is not affected by ICS or SCS." (PMID 35400078, 2022). "In patients with Adv+ pneumonia, the white blood cell (WBC) count, neutrophils percentage, and C-reactive protein (CRP) level were 7.1 ± 3.9 × 109/L, 70.66% ± 13.58%, and 7.92 (2.25, 66.75) (mean [IQR]) g/L, respectively, and 82.6% of patients showed a Procalcitonin (PCT) level of <0.5 ng/mL." (PMID 36161612, 2022). "Laboratory findings in patients with X-ray confirmed pneumonia showed four times higher the neutrophil-to-lymphocyte ratio (NLR; p = 0.035) and C-reactive protein (CRP; p = 0.016), and three times higher lactate dehydrogenase levels (LDH; p = 0.038) than patients without confirmed pneumonia." (PMID 35329864, 2022). "In February 2022, she suffered from pneumonia (CT data, increased C-reactive protein); hemoptysis was noted." (PMID 36286063, 2022). "Patients with and without pneumonia did not have remarkable differences in white blood cell count, C-reactive protein, creatinine, and lactate dehydrogenase and received similar therapeutic regimens." (PMID 35703556, 2022). "According to the NICE's guidelines, antibiotics should not be given to patients without a convincing clinical diagnosis of pneumonia, when their CRP is <20 mg/L." (PMID 35968461, 2022). "Neutrophil percentage, C-reactive protein (CRP), procalcitonin (PCT) and erythrocyte sedimentation rate (ESR) levels, and the percentage of polymorphonuclear leukocytes (PMNs) in the BALF were higher in patients with pneumonia than in the HC group." (PMID 36176576, 2022). "Intensive care needs, low lymphocyte count, and high ferritin had significant correlations with mortality; however, age, pneumonia, CT severity, CRP, and sedimentation were not significant." (PMID 35992514, 2022). "In the Omicron variant, the risk of pneumonia is related to high-risk factors, laboratory data such as LDH and CRP levels, and no vaccination." (PMID 35935257, 2022). "In our study, although ESR was shown to be significantly increased in groups with COVID-19 pneumonia, severe pneumonia, and intensive care requirements and who died, it was not prognostic and had less benefit for diagnosis and follow-up than CRP." (PMID 35992514, 2022). "In this study, we take it that plasma CRP on day 1 which is not affected by the use of ICS or SCS is a promising biomarker to identify pneumonia in AECPD patients especially in some cases where the interpretation of the chest imaging was blurred." (PMID 35400078, 2022). "These patients were significantly older, had significantly higher initial CRP levels, and had a significantly higher viral load in the lower respiratory tract than those CT-negative patients who did not develop pneumonia." (PMID 35239734, 2022). "Therefore, NLR correlated with post-CAP mortality better than traditional pneumonia scores (Pneumonia Severity Index, PSI; and Confusion, Urea, Respiratory rate and Blood pressure, aged 65 and older, CURB-65), WBC and CRP." (PMID 35408994, 2022). "In patients with AdV-infected pneumonia alone, immune-related indicators (total IgA, CRP, and LDH) were not significantly different between the two groups." (PMID 35979256, 2022). "Lack of cough or shortness of breath, a persistently elevated erythrocyte sedimentation rate and C-reactive protein despite antibiotic treatment, and a repeat chest radiograph without an opacity suggest an alternative diagnosis to pneumonia." (PMID 35251845, 2022). "Besides, neutrophil (Neu) counts, C-reactive protein (CRP), and procalcitonin (PCT) in peripheral blood are increased in AECOPD patients and more so in AECOPD complicated with pneumonia." (PMID 35400078, 2022).
pneumonia (continued). "Among children with severe pneumonia, the performance of sTREM-1 was also significantly better than that of PCT (AUROC = 0.632, 95% CI 0.547 to 0.716, P < 0.001) and CRP (AUROC = 0.552, 95% CI 0.461 to 0.644, P < 0.001) in identifying children at risk of 48-hour mortality." (PMID 35830474, 2022). "In summary, we find that AECOPD patients with pneumonia have more abnormal clinical features, similar short-term outcomes, and higher levels of inflammatory biomarkers, including CRP, PCT, OPN, and Neu but except sTREM-1 and EOS, compared to those with pneumonia." (PMID 35400078, 2022). "With regard to the laboratory findings, the CRP level was significantly higher in patients who developed pneumonia than in those who did not (1.0 ± 2.7 vs. 5.4 ± 8.7; P = .031)." (PMID 35239734, 2022). "When associations between respiratory outcomes and quantitative CT or blood biomarkers were assessed, a moderate correlation (a coefficient of 0.4–0.6) was present for pneumonia with CRP and fibrinogen, hypoxia with LDH and CRP, and respiratory failure with HAA (total or each lobe)." (PMID 35669915, 2022). "In addition, neutrophils, C-reactive protein (CRP), lactate dehydrogenase, and procalcitonin (PCT) were significantly higher in the severe pneumonia group than those in control children (P < 0.001)." (PMID 34558385, 2021). "We did not know the severity of the disease, such as C-reactive protein level, the pneumonia severity index, CURB-65, Modified Early Warning Score, and sequential organ failure assessment, which are associated with MACE occurrence and mortality." (PMID 34575202, 2021). "The odds of having RSV (+) pneumonia were 4.711 times greater for children with CRP of <20 mg/dL as opposed to ≥20 mg/dL." (PMID 34306103, 2021). "Besides, patients with pneumonia had clear evidence of infection, including elevated WBC, elevated NE%, high PCT, high CRP, or conditional pathogens from sputum culture or blood culture, and patients who improved after antibiotic treatment." (PMID 33747922, 2021). "Here, we demonstrate that reasoning for ab treatment depends on multiple factors such as an elevated CRP, clinical and radiological indication for pneumonia, as well as age of the patient rather than on the clinicians’ knowledge about RSV/test result." (PMID 33903713, 2021). "The median CRP level was much higher in children with severe pneumonia at admission as compared with the non-severe pneumonia cases while the difference in median concentration of the white cells were small between the two groups." (PMID 34412597, 2021). "In addition to the significant mean difference of CRP between RSV (+) and RSV (-) pneumonia, a cut-off level of 20 mg/L contributed to the regression model more than the other predictor variables." (PMID 34306103, 2021). "Evidence exists that point-of-care C-reactive protein (CRP) testing can help rule out pneumonia and guidelines recommend CRP testing for patients with symptoms of acute LRTI." (PMID 34205866, 2021). "Patients with CA/HCA-BSI more frequently presented neutrophilic leucocytosis and higher levels of C-reactive protein on admission, but a lower prevalence of radiologically confirmed pneumonia (61% in CA/HCA-BSI vs. 79% in non-BSI, 0.075)." (PMID 34572613, 2021). "One CTR participant developed pneumonia, not related to the supplement and another had high unexplained CRP value at the end of the study." (PMID 34424934, 2021). "Significantly, there were close linear correlations between MEG3 and neutrophils (R = 0.772, P < 0.001), CRP (R = 0.634, P < 0.001), and PCT (R = 0.727, P < 0.001), highlighting that MEG3 had a high possibility as a promising biomarker in severe pneumonia." (PMID 34558385, 2021).
pneumonia (continued). "In particular, patients in the SoC group had a higher PaO2/FiO2 at baseline (median 381, IQR 300–467 mmHg) and were less frequently diagnosed with pneumonia (68.1% of them); had lower LDH, AST, CRP, and ferritin; and higher neutrophils and lymphocytes count than the other three groups." (PMID 33967755, 2021). "C-Reactive protein is a good marker of inflammation, and it is not surprising that it is elevated in both SARS-CoV-2-associated pneumonia and control pneumonia cases." (PMID 33174170, 2021). "No indications for renal involvement or coagulation disorders were found in the macaques, and C-reactive protein (CRP) levels, a marker for pneumonia in humans, were also not afflicted." (PMID 34452537, 2021). "The aim of this study was to explore if consequent use of chest X-ray (CXR), when the physician is not sure of the diagnosis of pneumonia after clinical examination and CRP-testing, favors a more restrictive prescribing of antibiotics." (PMID 32705941, 2020). "The higher degree of suspicion before CRP, the less likely the suspicion degree shifted to ‘no longer suspicion of pneumonia’ (5% in the ‘quite sure’ group and 0% in the ‘sure’ group)." (PMID 33399009, 2020). "Of these, as many as 45% were regarded as ‘no pneumonia’ after CRP-testing, whereas the physician remained ‘unsure’ of the diagnosis in 26%." (PMID 33399009, 2020). "AUROCs for the diagnosis of pneumonia was 0.64 (95% CI: 0.56–0.72) for CRP; 0.59 (95% CI: 0.51–0.68) for PCT; 0.60 (95% CI: 0.52–0.69) for SAA; 0.41 (95% CI: 0.32–0.49) for NP; 0.63 (95% CI: 0.55–0.71) for CRP/NP; and 0.61 (95% CI: 0.53–0.70) for SAA/NP." (PMID 32997689, 2020). "We aimed to explore the benefit of CXR examination when the primary care physician was not sure of the pneumonia diagnosis after clinical examination and CRP-testing, and if consequently using it this way can alter the rate of antibiotic prescribing." (PMID 32705941, 2020). "Host factors CRP, IL-1β, hs-CRP, IL-8, and IL-6 levels in severe pneumonia patients were higher than in non-severe patients." (PMID 33065551, 2020). "Older (C-reactive protein (CRP); procalcitonin (PCT)) or newer (Serum amyloid A (SAA); neopterin (NP)) biomarkers may increase the accuracy of pneumonia diagnosis, but data are scarce and conflicting." (PMID 32997689, 2020). "Overall a difference in the distribution of CRP level groups (≤10, 11–25, 26–49, ≥50 mg/L) between those diagnosed with acute bronchitis and pneumonia was observed (χ2=335.1, p < 0.001) (Data not shown)." (PMID 31650886, 2020). "The levels of C-reactive protein (CRP) and high-sensitivity C-reactive protein (hs-CRP) were significantly increased in both non-severe and severe pneumonia patients." (PMID 33065551, 2020). "In 72 patients, there was no longer any suspicion of pneumonia according to the physician’s judgement after CRP testing (median CRP, 11 mg/L)." (PMID 33399009, 2020). "However, it can be difficult to differentiate pneumonia from other LRTIs by means of symptoms and signs, and the point-of-care test (POCT) named C-reactive protein (CRP) has been used since 1999 in Danish general practice." (PMID 31650886, 2020). "Delirious COPD patients had longer intubation time (p = 0.007), more often required reintubation (p = 0.019), had significantly higher levels of C-reactive protein (CRP) three days after surgery (p = 0.009) and were more often diagnosed with pneumonia (p < 0.001)." (PMID 32660083, 2020). "For pneumonia we used radiological defined opacity as well as CRP value, which were not validated in Indian children at the time of the study." (PMID 32085751, 2020). "CRP is a well-established biomarker of inflammation but has been considered as a non-specific marker in the pneumonia diagnosis." (PMID 31091284, 2019). "However, the patient developed worsening mitral regurgitation, increasing C-reactive protein (CRP) and concern for pneumonia 5 days after this de-escalation, prompting a switch to telavancin." (PMID 30858203, 2019).
pneumonia (continued). "Our present results illustrated that co-administration of MSC and LZD significantly decreased the plasma concentrations of systemic cytokines such as CRP, IL-8, IL-6, and TNF-α in MRSA-induced pneumonia compared with LZD treatment alone, which were in line with previous report." (PMID 31484796, 2019). "C-reactive protein (CRP) and procalcitonin (PCT) have been widely used in pneumonia management." (PMID 31091284, 2019). "Respiratory virus detections did not correlate to WBC or CRP values, signs and symptoms or prognosis of radiographically-verified pneumonia episodes." (PMID 30991957, 2019). "Outcome parameters are the use of CRP and chest X-ray, the percentage of GPs who guide their decision in requesting chest X-rays by CRP testing and the GP’s expectation regarding presence or absence of pneumonia." (PMID 31455104, 2019). "We found that PCT levels, but not CRP levels, significantly increased with increasing severity of pneumonia in both younger and elderly patients, although the degree of increase tended to be smaller in elderly patients under conditions of same severity." (PMID 30616612, 2019). "A low CRP (< 20 mg/l) can rule out pneumonia with reasonable certainty, irrespective of clinical signs and symptoms, while an elevated CRP level (> 100 mg/l) increases the chance of pneumonia and indicates a potential benefit from antibiotic treatment." (PMID 31747890, 2019). "A low CRP (<20 mg/l) can exclude pneumonia with reasonable certainty, irrespective of clinical findings while an elevated CRP (>100 mg/l) greatly increases the chance of pneumonia warranting antibiotic treatment." (PMID 31455104, 2019). "The mean CRP value was 146 mg/l in study episodes with pneumonia and 105 mg/l in study episodes without pneumonia (P < 0.001)." (PMID 30991957, 2019). "CRP levels did not significantly differ by pneumonia severity in both younger (p = 0.08) and elderly (p = 0.59) groups." (PMID 30616612, 2019). "C-reactive protein (CRP) can help to confirm or rule out pneumonia, taking clinical signs and symptoms into account." (PMID 31747890, 2019). "PCT levels, but not CRP levels, significantly increased with increasing pneumonia severity in younger and elderly patients, although the degree of increase tended to be lower in elderly patients compared to younger patients for the same severity." (PMID 30616612, 2019). "Adding CRP measurements to a clinical model in selected patients with an acute respiratory infection does not improve prediction of pneumonia, but does help in giving guidance on which patients to treat with antibiotics." (PMID 31747890, 2019). "CRP activity in goats has not been fully elucidated; there is one report showing changes in the concentration of CRP in this species, but only during pneumonia." (PMID 30223561, 2018). "Likewise CRP and leucocytes arelocated together, as are PH and COPD as well as smoking and pneumonia." (PMID 29257712, 2018). "Many of the ligands for CRP and SAP directly activated toll-like receptors (TLR), and CRP enhanced proinflammatory cytokine production by human peripheral blood mononuclear cells (PBMC) responding to S. pneumonia." (PMID 30483265, 2018). "The probabilities of developing pneumonia in patients with or without high CRP and low albumin levels were 100% (9/9) and 10.5% (4/38), respectively (p < 0.01)." (PMID 28938875, 2017). "NICE guidelines on pneumonia already recognise a role for CRP POCT in deciding whether to prescribe antibiotics, and the use of CRP POCT is increasing in the UK." (PMID 28969667, 2017). "The ROC analysis showed that, unlike procalcitonin, hs-CRP values were predictive of pneumonia (AUC 0.76, 95 % CI 0.72–0.79, p < 0.0001, cut-off value 61 mg/L), even after adjustment for possible confounders including nursing home residence and dementia." (PMID 26772604, 2016).
pneumonia (continued). "Although the CRP level and WBC count are used for diagnosing pulmonary infections, they are nonspecific and not helpful in differentiating bacterial and viral etiologies of pneumonia." (PMID 26840299, 2016). "There is actually only one study clearly concluding that procalcitonin is a better biomarker of pneumonia than CRP, while another reported that both tests have no advantages in clinical practice." (PMID 26772604, 2016). "The top clinical diagnoses recorded by the healthcare professionals, independent of the CRP levels, were acute URTIs combined (44.4%), followed by pneumonia (29.6%) and acute bronchitis (25.8%)." (PMID 26769226, 2016). "In this study, we did not observe either a marked increase in CRP levels or bacteremia and pneumonia in the patients treated with probiotics." (PMID 26987119, 2016). "In the present study, the prediction rate of initial serum CRP was lower than that of DNI and was not a predictor of superimposed pneumonia with ADHF, although there was a significant difference in serum CRP between the ADHF group and the pneumonia with ADHF group." (PMID 27682424, 2016). "In African children with WHO-defined clinical pneumonia, children with end-point pneumonia had higher plasma levels of CRP and PCT than those without, consistent with more extensive inflammation on chest radiograph." (PMID 26366571, 2015). "Eleven of 31 patients with a delayed decrease in CRP (35.5%) had postoperative infectious complications (early onset SSI, five; late onset SSI, three; pneumonia, one; CRBSI, one; and coincidence of early onset SSI and pneumonia, one)." (PMID 25888882, 2015). "The mean level of CRP in the blood samples of hospitalized patients with S. aureus pneumonia was not significantly elevated compared to patients with pneumonia triggered by MRSA." (PMID 26398276, 2015). "Most of the patients with pneumonia had CRP values > 50 mg/L, whereas none of the URTI patients had such high CRP values." (PMID 24886066, 2014). "Our results indicate that CRP and Lpc-2 can correctly distinguish most patients with severe pneumonia from those with nonsevere pneumonia and probable bacterial from probable nonbacterial causes." (PMID 24696240, 2014). "Lpc-2, CRP, and vWF levels were significantly higher in children with severe pneumonia than in those with nonsevere pneumonia." (PMID 24696240, 2014). "One study indicated that patients with Legionella pneumophila pneumonia had higher CRP levels than did those with pneumonia of any other etiology, independent of the severity of infection." (PMID 25371597, 2014). "A multivariate analysis was done to verify which parameters could be an independent predictors of mortality after balancing age, gender, initial severity of pneumonia, PT, PTA, ALT, Scr, CRP, PCT, and swab positive days." (PMID 24695420, 2014). "A significant reduction of body temperature, CRP level, and leukocytes blood count has been obtained by applying anthroposophic medicine, while neither complications nor pneumonia-related death occurred." (PMID 23762145, 2013). "The levels of IL-6, CRP and WBCs, as well as mean body temperature were significantly higher in the patients with pneumonia than in the patients without pneumonia." (PMID 23935729, 2013). "Third, although WBC and CRP was not a criterion for making the diagnosis of pneumonia, any infection and UTI, one must take into account that WBC was one of three criteria for the diagnosis of the subgroup of OI." (PMID 23118979, 2012). "In patients with CRP levels below 50 μg/ml, no dyspnea, and no daily subjective feeling of increased body temperature since the onset of cough, pneumonia is very unlikely at the time of consultation." (PMID 23245504, 2012). "sTREM-1 levels were significantly higher in the pneumonia group than in the nonbacterial pulmonary disease group, and this analysis was more sensitive and specific than analysis with CRP levels." (PMID 22809118, 2012).